RNU6-589P (RNA, U6 small nuclear 589, pseudogene)
Gene: Small nuclear RNA gene on chromosome X (102,678,707 to 102,678,813, reverse strand). Ensembl gene ENSG00000252294.
Homologues: Orthologues: chimpanzee U6 (99% identical), macaque U6 (97% identical), dog U6 (91% identical), guinea pig U6 (79% identical), guinea pig U6 (78% identical), dog U6 (76% identical), rat LOC120093925 (72% identical), mouse Gm55609 (68% identical). Paralogues in human: RNU6-44P (94% identical), RNU6-166P (93% identical), RNU6-41P (93% identical), RNU6-1152P (93% identical), RNU6-15P (93% identical), RNU6-259P (93% identical), RNU6-761P (93% identical), RNU6-1145P (92% identical), RNU6-12P (92% identical), RNU6-1316P (92% identical), RNU6-13P (92% identical), RNU6-25P (92% identical), and 1288 more.